BRCA1 (BRCA1 DNA repair associated)
Diseases named in the same sentence as BRCA1 in open-access papers (continued):
Sharing a sentence is not in itself a finding about the gene and the disease.
malignant mesothelioma (4 papers, 2015 to 2025). A malignant neoplasm of the pleura or peritoneum, arising from mesothelial cells. "This translates to a prevalence of 8.1% for BRCA2 variants in malignant mesothelioma compared to 2.1% for BRCA1 in this US based study." (PMID 37020472, 2023). "Thus, malignant mesothelioma has been reported to be associated with mutant Brca1 haploinsufficiency and was related to Fe2+ accumulation and to the decrease in ferritin expression since BRCA1 is a first line of defense against DSB, and the consequence was the oxidative DNA damage." (PMID 40149982, 2025). "A total of eighteen cases of malignant mesothelioma were analyzed for genetic alterations in BRCA1 and BRCA2 genes in this study." (PMID 37020472, 2023). "The aim of this study is to analyze the prevalence of somatic mutations in BRCA1 and BRCA2 in malignant mesothelioma and their putative impact on protein properties." (PMID 37020472, 2023). "Similar to these BRCA1 and BRCA2 associated malignancies, malignant mesothelioma patients with germline BRCA mutations are reported to have improved survival and better response to cisplatin-based regimens as well as benefit from PARPi therapy." (PMID 37020472, 2023). "Eighteen cases of malignant mesothelioma were retrieved from the archives and for next generation sequencing analysis of BRCA1 and BRCA2 genes." (PMID 37020472, 2023). "The aim of this study is to analyze the prevalence and frequency of somatic mutations in well-known cancer susceptibility genes, BRCA1 and BRCA2 in a small cohort of malignant mesothelioma patients and explore its putative impact on protein properties contributing to cancer pathogenicity." (PMID 37020472, 2023). "In the light of growing significance of somatic BRCA mutations, this study investigated the frequency of somatic BRCA1 and BRCA2 variants in a small cohort of malignant mesothelioma patients and found BRCA2 somatic variants to be much more common than BRCA1 variants." (PMID 37020472, 2023). "However, as seen in both studies, BRCA2 is altered more frequently than BRCA1 in malignant mesothelioma." (PMID 37020472, 2023). "Additionally, a decrease in the level of BRCA1 protein has been observed in the malignant mesothelioma cells with BAP1 deletion, while transduction of the mutants as well as WT BAP1 results in an increase in the level of BRCA1 protein." (PMID 30716094, 2019).
metabolic syndrome (4 papers, 2014 to 2024). A cluster of metabolic risk factors for CARDIOVASCULAR DISEASES and TYPE 2 DIABETES MELLITUS. "Many studies have identified complex interactions between metabolic syndrome (MetS) and BRCA1 germline mutations." (PMID 38612922, 2024).
metaplastic breast carcinoma (4 papers, 2013 to 2022). A group of invasive breast carcinomas characterized by the presence of an adenocarcinomatous component which is admixed with a dominant component that is composed of squamous cells, spindle cells, or mesenchymal cells. "The development of metaplastic breast cancer and relationship with BRCA1 are not well known." (PMID 33407746, 2021).
neutropenia (4 papers, 2017 to 2024). A decrease in the number of neutrophils found in the blood. "There has been some evidence that neutropenia after chemotherapy is more common in patients with BRCA1/2 mutations (32% vs. 10%), and patients with BRCA1/2 mutations tend to be more sensitive to ionizing radiation, because BRCA gene is involved in DNA repair and cell cycle control mechanisms." (PMID 39763583, 2024). "The study was stopped early after 13 patients (BRCA1 + n = 10; BRCA2 + n = 3) were accrued within 8 months with no grade 4 toxicities and only one patient requiring dose reduction due to grade 3 neutropenia." (PMID 29238749, 2017).
non-melanoma skin carcinoma (4 papers, 2004 to 2025). "The risk of non-melanoma skin cancer in women who carry a mutation in BRCA1 or BRCA2 is similar to that of non-carrier women." (PMID 38741145, 2024). "Among women included in the analysis, 379 (12%) of BRCA1 PV carriers, 646 (20%) of BRCA2 PV carriers and 645 (23%) of non-carriers experienced natural menopause prior to RRSO, a cancer diagnosis (apart from non-melanoma skin cancer) or interview." (PMID 40399999, 2025).
oral cancer (4 papers, 2014 to 2024). "While we show here that HOXA9 also appears to positively regulate BRCA1 expression in oral cancer cells, further studies will be required to fully understand how HOXA9 functions as a tumor suppressor in oral cancer." (PMID 24886209, 2014).
ovarian dysfunction (4 papers, 2020 to 2025). The inability of the ovaries to function. "Current studies consistently point to a strong association between BRCA1 mutation status and propensity of ovarian failure." (PMID 34193292, 2021). "BRCA1 mutation carriers have also been found to be more likely to have occult ovarian insufficiency." (PMID 31948486, 2020). "It further shows that ovarian dysfunction, which is more pronounced than the influence of BRCA2 mutations, is largely influenced by BRCA1 polymorphisms." (PMID 40385922, 2025). "Carriers of FMR1 premutation or BRCA1 mutation are at high risk of developing ovarian failure regardless of chemotherapy." (PMID 34193292, 2021).
psoriasis (4 papers, 2011 to 2024). An autoimmune condition characterized by red, well-delineated plaques with silvery scales that are usually on the extensor surfaces and scalp. "Thus, "Jak-STAT signaling pathway", "TNFR2 signaling Pathway" and "Role of BRCA1, BRCA2 and ATR in Cancer Susceptibility" are involved in the regulation of cellular responses to cytokines with the aim to providing an insight to the molecular mechanism involved in psoriasis." (PMID 21226955, 2011).
schizophrenia (4 papers, 2019 to 2025). A major psychotic disorder characterized by abnormalities in the perception or expression of reality.
seminoma (4 papers, 2009 to 2021). A radiosensitive malignant germ cell tumor found in the testis (especially undescended), and extragonadal sites (anterior mediastinum and pineal gland). "Both WEE1 and BRCA1 showed higher expression in seminoma compared to non‐seminoma samples according to the TCGA database, and the expression of BRCA1 was significantly correlated with TFAP2C." (PMID 32857912, 2020). "ESCO2 (establishment of cohesion 1 homolog 2) is tightly correlated with BRCA1-dependent and various cell-type specific carcinogenesis, and DAPP4 pluripotent factor is enriched in seminomas." (PMID 20015385, 2009).
Sepsis (4 papers, 2020 to 2023). Sepsis is defined as life-threatening organ dysfunction caused by a dysregulated host response to infection. "High expression of lncRNA MALAT1 along with low expression of breast cancer susceptibility gene 1 (BRCA1) were identified in septic mice and human skeletal muscle cells of sepsis." (PMID 31830649, 2020). "Taken together, lncRNA MALAT1 interacting with EZH2 stimulated AKT-1 phosphorylation and decreased BRCA1 expression, consequently aggravating the progression of sepsis, highlighting a promising therapeutic option for sepsis." (PMID 31830649, 2020). "Gene therapy with BRCA1 has been shown to decrease the systemic inflammatory response, multiple organ failure, and mortality, and consequently to improve survival in sepsis." (PMID 31830649, 2020). "To further explore the potential relationship between lncRNA MALAT1 and BRCA1, we induced a sepsis model using human skeletal muscle cells (HSMKMC 3500) by LPS treatment." (PMID 31830649, 2020). "It was indicated that lncRNA MALAT1 was significantly upregulated and BRCA1 was significantly downregulated in the sepsis group." (PMID 31830649, 2020). "The subcellular localization of BRCA1 in sepsis cells in response to sh-EZH2 or overexpressed EZH2 (oe-EZH2) was assessed by western blot analysis." (PMID 31830649, 2020). "Taken together, EZH2 regulated export from the nucleus of BRCA1 in skeletal muscle cells of sepsis via regulating the extent of AKT-1 phosphorylation." (PMID 31830649, 2020). "lncRNA MALAT1 was noted to regulate the expression and export from the nucleus of BRCA1 by recruiting zeste homolog 2 (EZH2) in skeletal muscle cells of sepsis." (PMID 31830649, 2020). "Furthermore, we detected the expression of BRCA1 in sepsis skeletal muscle cells after the expression of EZH2 was altered by western blot analysis." (PMID 31830649, 2020). "lncRNA MALAT1 interacting with EZH2 promoted the extent of AKT-1 phosphorylation and decreased BRCA1 expression and export from the nucleus, thus promoting skeletal muscle cell apoptosis and inflammatory responses and ultimately accelerating the progression of sepsis." (PMID 31830649, 2020). "Hence, the current study was designed with the aim of investigating the potential role of lncRNA MALAT1 in the initiation and development of sepsis, and we have demonstrated that lncRNA MALAT1 functions through the EZH2/BRCA1/AKT-1 axis to affect the progression of sepsis." (PMID 31830649, 2020). "Therefore, lncRNA MALAT1 could potentially regulate the expression and export from the nucleus of BRCA1 in sepsis." (PMID 31830649, 2020). "Collectively, the expressions of lncRNA MALAT1, BRCA1, and EZH2 were analyzed, with the predictive results obtained indicating that lncRNA MALAT1, BRCA1, and EZH2 are involved in the progression of sepsis." (PMID 31830649, 2020).
Stroke (4 papers, 2012 to 2023). Sudden impairment of blood flow to a part of the brain due to occlusion or rupture of an artery to the brain. "Both TGR5 siRNA or BRCA1 siRNA significantly exacerbated stroke outcomes and aggravated BBB permeability after MCAO (P < 0.05), when compared with scramble siRNA group at 24 h after MCAO." (PMID 32381096, 2020). "Young rats also had better synchronized gene expression as was illustrated by the coordinated co-expression of genotoxic stress-induced genes Brca1 and Irf1 at day 3 post-stroke." (PMID 23251410, 2012). "Furthermore, our data demonstrated that TGR5 or BRCA1 knockdown significantly reverses the neuro-protection of INT777 on stroke outcomes, as well as decreasing ZO-1 and occludin expression." (PMID 32381096, 2020). "TGR5 siRNA and BRCA1 siRNA significantly inhibited expressions of BRCA1 and Sirt1, aggravated BBB permeability and exacerbated stroke outcomes after MCAO." (PMID 32381096, 2020). "The results highlight TGR5/BRCA1/Sirt1 signaling as a critical contributor to alleviate BBB damage and as a novel target for brain edema in diseases characterized by BBB damage, such as stroke, inflammatory diseases, and neurodegenerative diseases." (PMID 32381096, 2020).
tongue SCC (4 papers, 2015 to 2025). "Here, we show the long noncoding RNA (lncRNA) LINC01011, which we termed cisplatin-sensitivity-associated lncRNA (CISAL), controls mitochondrial fission and cisplatin sensitivity by inhibiting BRCA1 transcription in tongue SCC (TSCC) models." (PMID 32000125, 2020). "Similarly, in tongue squamous cell carcinoma, the BRCA1-miR-593-5p-MFF axis regulates cisplatin sensitivity by modulating mitochondrial fission and apoptosis, further highlighting the complex role of BRCA1 in therapeutic responses." (PMID 40224184, 2025).
transitional cell carcinoma (4 papers, 2014 to 2024). A malignant neoplasm arising from the transitional epithelium, usually affecting the urinary bladder, ureter, or renal pelvis. "Notably, HGSC with BRCA dysregulations, including BRCA1/BRCA2 mutations and BRCA1 promoter hypermethylation, are associated with specific morphological “SET” patterns: Solid, pseudoEndometrioid, and Transitional cell carcinoma-like histology." (PMID 32269964, 2020).
Uterine leiomyoma (4 papers, 2022 to 2024). The presence of a leiomyoma of the uterus. "Hysterectomy was performed in five of six BRCA1 pathological variants (Patient 1 of the BRCA1 pathological variant group had already had a hysterectomy due to a history of uterine fibroids) and 5 of 12 BRCA2 pathological variants." (PMID 36849964, 2023).
von Hippel-Lindau syndrome (4 papers, 2008 to 2025). "For instance, Hereditary Breast and Ovarian Cancer (HBOC) is associated with mutations in BRCA1/2, Von Hippel-Lindau (VHL) syndrome is associated with mutations in the VHL gene, and Hereditary Retinoblastoma is associated with mutations in the RB1 gene." (PMID 40695959, 2025). "The largest number of concurrent CVs was observed in the VHL gene (von Hippel-Lindau syndrome, MIM# 193300), followed by BRCA1/BRCA2 (hereditary breast cancer syndrome, MIM# 113705, 600185)." (PMID 18974781, 2008).
Werner syndrome (4 papers, 2011 to 2023). "Such interactions can be seen when hypermethylation inactivates the CpG island of the promoter of the DNA-repair genes hMLH1, BRCA1, MGMT (O6-methylguanine–DNA methyltransferase), and the gene associated with Werner’s syndrome (WRN)." (PMID 22408433, 2012). "Previous DCC studies of Werner syndrome and control cells suggested that DCC defect per se is not sufficient to cause significant genomic instability, but requires absence or dysfunction of "caretaker" genes such as ATR, BRCA1 or WRN." (PMID 21824431, 2011).
acute promyelocytic leukemia (3 papers, 2011 to 2023). An aggressive form of acute myeloid leukemia (AML), characterized by arrest of leukocyte differentiation at the promyelocyte stage, due to a specific chromosomal translocation t(15;17) in myeloid cells. "The naturally occurring BRCA1 BRCT mutant M1775R also produced unusual looking promyelocytic leukemia nuclear bodies (PML-NBs), suggesting M1775R upsets the normal processing of the BASC." (PMID 21666281, 2011). "Promyelocytic leukemia nuclear bodies (PML-NBs) are important for the assembly and disassembly of protein complexes, including those with RAD51, RPA, and BRCA1 necessary for HRR (for a recent review)." (PMID 21666281, 2011).
ampullary carcinomas (3 papers, 2016 to 2024). "In ampullary cancers, we here show for the first time a frequency of 14.3% BRCA1/BRCA2 mutations after a combination of direct founder mutation testing and full gene analysis in archival tissue with NGS." (PMID 27532258, 2016).
amyotrophic lateral sclerosis (3 papers, 2017 to 2021). Amyotrophic lateral sclerosis (ALS) is a neurodegenerative disease characterized by progressive muscular paralysis reflecting degeneration of motor neurons in the primary motor cortex, corticospinal tracts, brainstem and spinal cord. "To this end, using cell-specific microarrays in CD11b+ microglia, we recently identified DNA damage pathway and in particular the tumor suppressor gene breast cancer susceptibility gene 1 (Brca1) upregulation in an animal model of amyotrophic lateral sclerosis (ALS)." (PMID 28420963, 2017). "Accordingly, BRCA1 expression in microglia was upregulated in human amyotrophic lateral sclerosis spinal cord samples compared to controls." (PMID 34222870, 2021). "Rather, in a mouse model of amyotrophic lateral sclerosis, BRCA1 expression did not appear dysregulated in motoneurons, but an upregulation of BRCA1 was identified in microglia." (PMID 34222870, 2021). "Interestingly, this BRCA1 colocalization was not seen with alpha-synuclein or TARDBP (TAR DNA-binding protein) inclusions, histopathological features associated with Parkinson’s disease and amyotrophic lateral sclerosis, respectively." (PMID 34222870, 2021).
benign breast tumours (3 papers, 1996 to 2024). "The hypermethylation of BRCA-1 promoter in patients with benign breast tumours was grouped as high-risk, and the detection of their methylation is helpful for the early diagnosis of BC." (PMID 38723244, 2024).
bowel cancer (3 papers, 2007 to 2024). "Male carriers of BRCA1/2 mutations (hereafter referred to as male carriers) have an increased risk of prostate (substantial for BRCA2) and bowel cancer." (PMID 17285126, 2007). "Since the study commenced bowel cancer risks have become less clear, especially for BRCA1." (PMID 17285126, 2007).
cervical tumors (3 papers, 2014 to 2020). "Our results revealed an increased protein level of FANCD2, RAD51, BRCA1 and BRIP1 in the NCR compared to CR cervical tumor nuclei." (PMID 24708616, 2014). "Increased protein levels of FANCD2, RAD51, BRCA1, and BRIP 1 (BACH1) in NCR compared to CR cervical tumors groups were confirmed on the validation set." (PMID 24708616, 2014). "We observed a significantly increased protein levels of FANCD2, BRCA1, RAD51 and BRIP1 in the nuclei of the NCR compared to the CR cervical tumors." (PMID 24708616, 2014). "In addition, a previous study demonstrated that the expression/protein levels of BRCA1 were increased in noncomplete response (NCR) compared to complete response (CR) cervical tumors." (PMID 32879886, 2020).
cyst (3 papers, 2019 to 2022). A sac-like closed membranous structure that may be empty or contain fluid or amorphous material. "Specifically, these genes have been related to the diapause reproductive mode, such as BRCA1 and p8, and also with cyst resistance to stress, such as artemin, SGEG, Arp-CBP, and SGEG1 and SGEG2." (PMID 35432444, 2022). "The multiple regression analysis supports that five of these genes (SGEG, artemin, Arp-CBP, p8, and BRCA1) could be important predictor variables for cyst production in this population, given that all of them were included in the highest-ranking model." (PMID 35432444, 2022). "These genes participate at different levels, in the formation of the cyst chorion (e.g., SGEG and Arp-CBP), in the control of cellular division (e.g., BRCA1 and p8), or as molecular chaperones whose function is to avoid denaturation of the proteins (e.g., artemin, ArHsp21, ArHsp22, and p26)." (PMID 35432444, 2022).
genitourinary cancer (3 papers, 2022 to 2024). "For example, locally advanced or metastatic genitourinary cancer patients with BRCA1/2 mutations may be treated with poly ADP-ribose polymerase (PARP) inhibitors." (PMID 36451132, 2022). "In the present study, previously suggested associations of BRCA1/2 PVs with risks of other genitourinary cancers and melanoma were not replicated." (PMID 35077220, 2022).
intraepithelial neoplasia (3 papers, 2016 to 2024). A precancerous neoplastic process that affects the squamous, glandular, or transitional cell epithelium without evidence of invasion. "BRCA1 haploinsufficiency in normal fallopian tube epithelium may lead to up-regulation of E2F3b and increased proliferation before the development of intraepithelial neoplasia." (PMID 27027446, 2016).
intrahepatic cholangiocarcinoma (3 papers, 2020 to 2025). A carcinoma that arises from the intrahepatic bile duct epithelium in any site of the intrahepatic biliary tree. "We presented a case of a patient with advanced intrahepatic cholangiocarcinoma (iCCA) harboring dual somatic homologous recombination repair (HRR) gene pathogenic variants, specifically BRCA1 and PALB2, who achieved PR lasting approximately 7 months following salvage treatment with olaparib." (PMID 40822464, 2025).